EPN1 (epsin 1)
Description:
Binds to membranes enriched in phosphatidylinositol 4,5-bisphosphate (PtdIns(4,5)P2). Modifies membrane curvature and facilitates the formation of clathrin-coated invaginations (By similarity). Regulates receptor-mediated endocytosis.
Tractability: Antibody: its Gene Ontology location is reachable by antibodies, with high confidence; UniProt places it where antibodies can reach, with medium confidence; the Human Protein Atlas places it where antibodies can reach. PROTAC: UniProt records ubiquitination sites on it; ubiquitination databases record sites on it; its protein half-life has been measured.
Gene: Protein-coding gene on chromosome 19 (55,675,109 to 55,709,858, forward strand). Ensembl gene ENSG00000063245.
Subcellular location: Cytoplasm; Cell membrane; Nucleus; Membrane, clathrin-coated pit
Subcellular location (Human Protein Atlas): Cytosol; Plasma membrane; Nucleoplasm; Vesicles
Pathways (Reactome):
Vesicle-mediated transport: Cargo recognition for clathrin-mediated endocytosis; Clathrin-mediated endocytosis
Signal Transduction: EGFR downregulation
Gene Ontology:
Molecular function: molecular sequestering activity; protein binding; phospholipid binding
Biological process: negative regulation of sprouting angiogenesis; endocytosis
Cellular component: clathrin vesicle coat; cytosol; plasma membrane; clathrin-coated pit; cytoplasm; nucleus
Genetic constraint (gnomAD): Loss-of-function variants: 26 observed, 49 expected, observed/expected ratio (o/e) 0.53, 90% interval 0.39 to 0.74. The synonymous counts are far from expectation, so gnomAD's model fits this gene poorly and the ratio says little. Missense variants: 768 observed, 753.61 expected, observed/expected ratio (o/e) 1.02, 90% interval 0.96 to 1.08. Synonymous variants: 399 observed, 333.99 expected, observed/expected ratio (o/e) 1.19, 90% interval 1.1 to 1.3.
Homologues: Orthologues: chimpanzee EPN1 (95% identical), macaque EPN1 (95% identical), pig EPN1 (95% identical), mouse Epn1 (95% identical), rat Epn1 (95% identical), dog EPN1 (93% identical), tropical clawed frog epn1 (69% identical), zebrafish epn1a (60% identical), Drosophila melanogaster lqf (41% identical), zebrafish epn1b (32% identical), Caenorhabditis elegans epn-1 (32% identical), guinea pig Epn1 (9% identical). Paralogues in human: EPN2 (48% identical), EPN3 (48% identical), ENTHD1 (24% identical), CLINT1 (24% identical), MYCBPAP (16% identical).
Diseases named in the same sentence as EPN1 in open-access papers:
EPN1 is named in the same sentence as 22 diseases in open-access papers, as found by Europe PMC text mining. Sharing a sentence is not in itself a finding about the gene and the disease. The quoted sentences say what the papers report.
ependymoma (3 papers, 2018 to 2025). A WHO grade II, slow growing tumor of children and young adults, usually located intraventricularly. "Here, we performed more a detailed analysis by comparing different culture conditions of ependymoma, focusing on two patients (EPN1 and EPN3)." (PMID 37508868, 2023). "Fusions (seen as larger proteins than wild-type rela) were detected in all cells derived from ST ependymomas (BXD-1425EPN, DKFZ-EP1, EPN1) but none of the PF cells (EPN8, EPN9, EPN10)." (PMID 30559935, 2018).
amyotrophic lateral sclerosis (1 paper, 2025). Amyotrophic lateral sclerosis (ALS) is a neurodegenerative disease characterized by progressive muscular paralysis reflecting degeneration of motor neurons in the primary motor cortex, corticospinal tracts, brainstem and spinal cord. "KEGG analysis revealed two processes, Huntington’s disease and Amyotrophic lateral sclerosis, whereas the REACTOM database revealed one item: EGFR downregulation, with three genes, protein-tyrosine phosphatase (PTP)-PEST (PTPN12), epidermal growth factor receptor (EGFR), and epsin 1 (EPN1)." (PMID 40269194, 2025).
cervical cancer (1 paper, 2022). A primary or metastatic malignant neoplasm involving the cervix. "For example, high CHRM3 levels are linked to invasion and metastasis in colon cancers; loss of EPN1 was linked to elevated VEGFR2 degradation and disorganized angiogenesis; and elevated PTGER3 levels was linked to shorter survival times in cervical cancers." (PMID 35991579, 2022).
endothelial dysfunction (1 paper, 2020). In vascular diseases, endothelial dysfunction is a systemic pathological state of the endothelium (the inner lining of blood vessels) and can be broadly defined as an imbalance between vasodilating and vasoconstricting substances produced by (or acting on) the endothelium. "As aberrant calcium signaling and ER stress can substantially contribute to endothelial dysfunction and atherogenesis, we investigated the connection between epsin 1 and IP3R1 in cholesterol-treated endothelial cells." (PMID 32770009, 2020).
lymphoma (1 paper, 2021). A malignant (clonal) proliferation of B- lymphocytes or T- lymphocytes which involves the lymph nodes, bone marrow and/or extranodal sites. "In contrast, critical components of CME, EPN1 and PICALM, were not essential in Ramos cells or most other lymphoma cell lines (Fig EV4D)." (PMID 34323351, 2021).
medulloblastoma (1 paper, 2021). A malignant, invasive embryonal neoplasm arising from the cerebellum. "EPN1 was identified as one of the hub genes in pediatric medulloblastoma by multiple-microarray analysis." (PMID 35004283, 2021).
meningioma (1 paper, 2021). A generally slow growing tumor attached to the dura mater. "EPN1, EXOSC4, H2AX, and MZT2B not only showed significant differences between meningioma molecular subtypes but also had the potential to be the marker genes of specific meningioma subtypes." (PMID 35004283, 2021). "The expression of EPN1, EXOSC4, H2AX, and MZT2B was related to both WHO grades and age of patients and was significantly different between normal meningeal tissues and meningiomas." (PMID 35004283, 2021). "Among 32 key hub genes screened, EPN1, EXOSC4, H2AX, and MZT2B not only showed significant differences between meningioma molecular subtypes but also had the potential to be the marker genes of specific meningioma subtype." (PMID 35004283, 2021).
virus infection (1 paper, 2025). "In summary, we describe the acquisition of the epsin 1 interactome upon virus infection and uncover Neo1 as a novel proviral host factor for IAV." (PMID 40623098, 2025). "To identify IAV internalization receptor candidates, we acquired the epsin 1 interactome during virus infection through proximity labelling given the described role of epsin 1 in IAV internalization." (PMID 40623098, 2025). "Here, we performed proximity labelling to identify proteins in the vicinity of epsin 1 during virus infection as a means to uncover IAV internalization receptors." (PMID 40623098, 2025). "As epsin 1 can interact with ubiquitinated receptors to facilitate their uptake we hypothesized that epsin 1 may be in the vicinity of internalization receptors upon virus infection." (PMID 40623098, 2025).
tumor (7 papers, 2017 to 2023). "The PCA plot showed the close clustering of EPN3 in vitro samples with the primary tumor tissue; however, it also showed clear separation from EPN1 in vitro samples." (PMID 37508868, 2023). "EPN1 was established in-house from a second recurrence, and analysis of samples taken from the primary tumour and two recurrences all showed low numbers of BLBP positive cells consistent again with the CSC hypothesis." (PMID 33925302, 2021). "Interestingly, EPN1 in vitro samples were clustered closely with the Endo samples, suggesting endothelial cell dominance in this group, which may have skewed the transcriptomic profiles away from the primary tumor tissue." (PMID 37508868, 2023). "The genes validated as targets of miR-365b included EPN1, H2AFY, PI3KR3 and VGLL4, in which all have been reported as players in tumor biology, and interestingly both VGLL4 and EPN1 were shown to be involved in regulation of Wnt-signaling, a pathway that is dysregulated in MM40." (PMID 35840794, 2022). "While a potential role in regulating tumor angiogenesis has been proposed for EPN1 and EPN251,52, our results show that EPN1 overexpression does not phenocopy any of the investigated EPN3 effects, thereby pointing to a specific modality of transformation by EPN3, at least in BC." (PMID 32541686, 2020). "In mouse vascular endothelium, depletion of epsin-1 and -2 inhibits tumor growth by impairing the endocytosis and degradation of vascular endothelial growth factor receptor 2 (VEGFR2), leading to excessive VEGF signaling and results in disorganized vasculature and nonproductive tumor angiogenesis." (PMID 29954076, 2018).
cancer (2 papers, 2012 to 2022). A tumor composed of atypical neoplastic, often pleomorphic cells that invade other tissues. "Epsin1, encoded by EPN1, is related to angiogenesis in cancer patients." (PMID 36320085, 2022). "Other genes down-regulated by rosiglitazone belonged mainly to two functional groups: “cancer” (RPS27A, SORBS2, STIP1, FGA, FGFR2, SSH3, EPN1) and cell death (SORBS2, STIP1, GAS2, EPN1)." (PMID 22761953, 2012).
infection (2 papers, 2021 to 2025). The state of being infected such as from the introduction of a foreign agent such as serum, vaccine, antigenic substance or organism. "These criteria yielded 1 potential GFP interactor, which was discarded from further studies, and 42 potential epsin 1 interactors: 8 specific to mock-infection, 13 to IAV-infection and 21 shared across both conditions." (PMID 40623098, 2025). "In sum, we identify multiple proteins in the vicinity of epsin 1 during infection, providing a list of host factors potentially involved in CME of IAV." (PMID 40623098, 2025). "From our analysis of the interactome hits for plasma membrane localization and infection-induced epsin 1 vicinity, Neo1 emerged as a promising candidate for an internalization receptor." (PMID 40623098, 2025). "Here, we performed proximity labelling centered on epsin 1 during infection and uncover Neo1 as a potential IAV internalization receptor." (PMID 40623098, 2025). "We observed a similar phenotype when the infection foci contained caveolin-1- or epsin-1-depleted cells." (PMID 34781738, 2021). "Since our system relies on epsin 1 overexpression, it is possible that sensitive interactions are considered non-enriched yet a potential role in infection should not be ruled out." (PMID 40623098, 2025).
cardiovascular diseases (1 paper, 2023). "Epn1 is an endocytic accessory protein that plays an important role clathrin-mediated endocytosis and has been suggested to control endocytotic sorting processes in cardiovascular diseases." (PMID 37597109, 2023).
EPN1 also shares sentences with these, for which no sentence is quoted: colon cancers (1 paper); glioblastoma (1); hepatocellular carcinoma (1); Huntington disease (1); lung carcinoma (1); lung squamous cell carcinoma (1); mammary carcinoma (1); osteosarcoma (1); pancreatic cancer (1); prostate carcinoma (1).